CCL2 (C-C motif chemokine ligand 2)
Diseases named in the same sentence as CCL2 in open-access papers (continued):
Sharing a sentence is not in itself a finding about the gene and the disease.
dementia (46 papers, 2006 to 2025). Loss of intellectual abilities interfering with an individual's social and occupational functions. "Elevated serum levels of CCL2 show a positive correlation with in vivo HIV-1 viral load and disease progression, as well as the development of HIV-associated dementia." (PMID 38005838, 2023). "(2020), investigating four weeks of two supervised exercise protocols (aerobic and strength training) in the elderly with dementia, has noted a decrease in CCL-2/MCP-1 serum levels in both supervised exercise protocols." (PMID 36685603, 2022). "This study describes the role of the CCR2/CCL2-axis in the communication between the brain and the immune system to combat dementia." (PMID 34172073, 2021). "Elevated CCL2-signaling in the brain might exacerbate the progression rate of AD-related pathology during pre-dementia stages." (PMID 22303443, 2012). "Similarly, the time to conversion to dementia was shorter in MCI-AD (i.e. prodromal AD) cases who had CCL2 levels in the highest tertile when compared to those in the lowest tertile (p<0.003)." (PMID 22303443, 2012). "In addition, some reports have shown a possible association between CCL2 levels in CSF and the development of HIV-associated dementia, suggesting that this chemokine could be used as a biomarker of disease progression." (PMID 32185196, 2020). "Moreover, a genetic polymorphism in the CCL2 gene (2518G/A), linked to an increased production of the protein, is associated with increased risk of HIV-1 infection, disease progression and development of HIV-associated dementia." (PMID 25608886, 2015). "Moreover, increased levels of the CCL2 protein in serum of both civilian TBI patients and military blast-induced mild TBI cases have been demonstrated and found to be a potential risk factor for subsequent dementia." (PMID 25153123, 2014). "In our observations, we noted an increase in peripheral CCL2 in patients with MCI-AD and AD dementia." (PMID 38658964, 2024). "Taken together, our results highlight a general mechanism that is needed to combat dementia, in which the CCR2/CCL2 axis, together with additional chemokines, such as Cxcl12, regulate the communication pathway between the brain and the immune system." (PMID 34172073, 2021). "CCL2 is overproduced during the HIVE and accumulates in the CSF and brains of immunocompromised patients with HIV-related dementia." (PMID 32185196, 2020). "With this purpose, CCL11/eotaxin, CXCL-10/IP-10, CCL2/MCP-1, and CCL4/MIP-1β levels were measured in the CSF of 87 PD patients (16 with dementia diagnosis) and 33 controls." (PMID 25386381, 2014). "The results show that CSF chemokine concentration of MCP-1/CCL2, MIP-1α/CCL3, MIP-1β/CCL4, RANTES/CCL5, IL-8/CXCL8 and fractalkine/CX3CL1 is positively correlated with the severity of dementia and the viral load, indicating HIV induced brain damage." (PMID 16712719, 2006). "We observed an increase in CCL2 levels in both MCI-AD and AD dementia patients." (PMID 38658964, 2024). "Indeed, we found that CCL2 positively correlated with CSF markers of neuroinflammation, as chitinase-3-like protein 1 (YKL-40) and soluble triggering receptor expressed on myeloid cells 2 (sTREM-2) in AD dementia." (PMID 38658964, 2024).
peritonitis (46 papers, 2009 to 2025). Inflammation of the peritoneum (tissue that lines the abdominal wall and covers most of the organs in the abdomen). "As expected, CLP-induced peritonitis was associated with strong systemic and local upregulation of pro-inflammatory cytokines IL-6, CCL2, and TNF as well as upregulation of anti-inflammatory IL-10 compared to sham animals." (PMID 38562925, 2024). "It was demonstrated that IκBζ‐deficient macrophages had an impaired secretion of CCL2 when challenged with LPS or bacterial peptidoglycan, whereas IκBζ‐deficient mice displayed a reduced CCL2 secretion and monocytes infiltration in the zymosan peritonitis model." (PMID 36245291, 2022). "During the resolving phase of E. coli-induced peritonitis, marked by an increased recruitment of mononuclear cells, lower numbers of these cells and CCL2 levels were found in the peritoneal cavity of GILZ-deficient mice (GILZ−/−) when compared to WT." (PMID 37408237, 2023). "In the mouse model of acute peritonitis, Iripin-1 enhanced the production of the anti-inflammatory cytokine IL-10 and chemokines involved in neutrophil and monocyte recruitment, including MCP-1/CCL2, a potent histamine-releasing factor." (PMID 36756125, 2023). "Early production of CCL3, as well as CCL2 and cytokines such as IL-1β, IL-6, IL-12, and IL-1Ra, was observed in an acute antigen-induced peritonitis model, showing that peritoneal-resident cells are an important source of these mediators." (PMID 30937315, 2019). "In this study, the effluent from three patients with peritonitis induced CCL2 and CXCL8 secretion by mesothelial cells while effluent from stable patients showed only background activity." (PMID 27527598, 2016). "For example, isoQC—but not QC—catalyzes the pGlu modification of the monocyte chemoattractant protein-1 (MCP-1; also designated CCL2) and thereby stimulates monocytic infiltration into the peritoneum of mice in the thioglycollate-induced peritonitis model." (PMID 25666182, 2015). "CCL2 has been suggested as an important chemoattractant of monocytes and macrophagesto the peritoneal region, being the main cells present in inflammatory processes,especially in peritonitis episodes." (PMID 34032817, 2021). "The Cxcl13+ FALC cover cell cluster was distinguished by the expression of the monocyte chemoattractants Ccl2 and Ccl7 and the neutrophil chemoattractants Cxcl1 and Cxcl10, suggesting a role for these cells in orchestrating the recruitment of inflammatory cells during peritonitis." (PMID 32294409, 2020). "Several studies indicate that Ccl2 and Ccl7 are the primary agonists of Ccr2, in which ablation of either of these ligands reduced monocyte recruitment from bone marrow to peripheral vessels in thioglycollate-induced peritonitis and Listeria monocytogenes infection." (PMID 25595590, 2015). "The group sampled 2 h following treatment exhibited a decrease in the concentrations of 35 proteins in animals subjected to laparoscopic lavage, while four proteins (TGFBR3, LPL, CCL2 and IL6) were found in elevated concentrations compared to time-matched peritonitis controls." (PMID 40102905, 2025).
cervical carcinoma (45 papers, 2005 to 2026). A carcinoma arising from either the exocervical squamous epithelium or the endocervical glandular epithelium. "Altogether, we conclude that NMB is produced by cervical cancer cell, causing the reprograming and activation of Schwann cells, which then secrets CCL2 to initiate PNI of cervical cancer." (PMID 39214988, 2024). "The expression of CCL2 in cervical cancer cells causes the recruitment of macrophages, which supports the progression of the cervical tumor." (PMID 36403055, 2022). "The combined examination of serum NMB and CCL2 may serve as diagnostic indicators to predict PNI before operation in cervical cancer patients, and help to identify whether these patients could choose NSRH surgery." (PMID 39214988, 2024). "CCL2 is overexpressed in various cancers and is associated with poor prognosis in breast, colorectal, and thyroid cancers, and a lack of CCL2 is associated with increased survival in patients with cervical cancer." (PMID 36900416, 2023). "MCP-1, also known as Ccl2, triggers the infiltration and activation of cells of the monocyte-macrophage lineage and has been linked with antitumor immunity and cervical cancer." (PMID 23316105, 2012). "CCL2 plays a crucial role in regulating immune suppression in the TME and is closely linked to poor prognoses in cervical cancer patients." (PMID 41583906, 2026). "The serum level of CCL2 in cervical cancer patients was also examined, and it was significantly higher in patients with PNI, positively correlated with serum NMB, and significantly predicted PNI." (PMID 39214988, 2024). "In a prior study involving 93 cervical cancer tissue samples and using the RNA in situ hybridization technique, authors found that CCL2 expression was elevated in 47 samples." (PMID 39727946, 2024). "Clinically, combined examination of serum NMB and CCL2 levels was suggested to effectively predict PNI in cervical cancer patients." (PMID 39214988, 2024). "SCs migrate to the vicinity of the tumor and secrete CCL2 under signals derived from cervical cancer cells, which acts as a potent chemoattractant, inducing CCR2+ cervical cancer cells to undergo epithelial–mesenchymal transition (EMT) and move along neurites." (PMID 39061654, 2024). "In brief, the results indicate that high-dose irradiated CAFs regulate M2 phenotype polarization via increased secretion of CCL2, which subsequently induces radioresistance in cervical cancer." (PMID 36900416, 2023). "One study differently claimed that CCL2 is highly expressed in cervical cancer cells, and its expression level is related to the number of tumor-associated macrophages." (PMID 36403055, 2022). "When binding to its receptor CCR2 on the membrane of cervical cancer cells, the CCL2 generated from Schwann cells promoted cancer cell proliferation, migration, and invasion." (PMID 36403055, 2022). "Patients with cervical cancer who lack CCL2 expression have a better prognosis and longer overall survival." (PMID 36403055, 2022). "In cervical cancer, serum CCL2 is elevated in cervical adenocarcinoma, according to the most recent study." (PMID 36403055, 2022). "Although cervical cancer cells produce fewer chemokines, they engage monocytes and stimulate the production of CCL2 by monocytes, thus promoting macrophage aggregation within the tumor microenvironment." (PMID 36403055, 2022). "Experiments have shown that cervical cancer cells secreted prostaglandin (PG) E2 and IL-6 to induce M2 phenotype and produce CCL2 to promote the recruitment of monocytes at the tumor site." (PMID 34717710, 2021). "In cervical cancer, Schwann cells were mobilized into the cancer tissue, and metastasis was promoted by increasing the MMP secretion of cancer cells via CCL2, causing serum CCL2 to increase." (PMID 34445235, 2021). "In the following studies, the same group showed that hyperplastic squamous epithelium, in addition to cervical cancer, has high CCL2 expression and an increased number of infiltrating macrophages." (PMID 34833360, 2021).
cervical carcinoma (continued). "Anticancer screening of ADG-2e against cervical cancer cells, HeLa CCL2, and BT549 mammary gland ductal carcinoma showed significant inhibition of cancer cell proliferation." (PMID 34959352, 2021). "CCL2 is related to both primary tumor development and metastasis in various cancers including cervical cancer." (PMID 32064233, 2020). "Our results found that the serum CCL2 levels were increased in cervical cancer samples, especially in patients with AC." (PMID 32064233, 2020). "SCs arrive at the site of cancer cells and secrete CCL2 as a strong chemoattractant which then induces CCR2+ cervical cancer cells to move along neurites." (PMID 32064233, 2020). "CCL2 also influenced cellular proliferation and morphological changes to support cervical cancer cell migration toward SCs." (PMID 32064233, 2020). "Although CCL2 is also a ligand of CCR2, we found that CCL8 expression was increased more than CCL2 expression in hypoxic cervical cancer cells, competitively binding with CCR2, which mediated macrophage infiltration." (PMID 31263103, 2019). "Expression of CCL2 has also been found to be decreased in prostate adenocarcinoma compared to benign prostate hyperplasia and cervical carcinomas compared to normal or hyperplastic squamous epithelium." (PMID 15900302, 2005). "It was also found that CCL2 expression was elevated in cervical cancer." (PMID 39727946, 2024). "As expected, CCL2 is also a significant participant in PNI in cervical cancer." (PMID 39061654, 2024). "In this study, both tumor-derived NMB and Schwann cell-derived CCL2 could be detected in the plasma of cervical cancer patients and were clearly increased in those with PNI." (PMID 39214988, 2024). "The elevated serum NMB and CCL2 levels may be useful for the decision-making to nerve sparing during hysterectomy surgery of cervical cancer patients." (PMID 39214988, 2024). "In addition, high-dose irradiated CAFs promote macrophage M2 polarization in cervical cancer through the secretion of chemokine (C-C motif) ligand 2 (CCL2)." (PMID 36900416, 2023). "Another study showed that Cx43 may be modified by SUMO-1/2/3 in human cervical cancer cells, HeLa-CCL2 transfected with Cx43, indicating that Cx43 SUMOylation could be cell-type-dependent." (PMID 36769280, 2023). "Studies have shown that CCL2 is present in cervical cancer cells and their precancerous lesions." (PMID 36403055, 2022). "Furthermore, the expression of CCL2 is elevated in breast, ovarian, and cervical cancer, indicating the pivotal role of CCL2 in gynecological malignancies." (PMID 36403055, 2022). "Based on these results, the CCL2/CCR2 axis may serve as a potential marker for cervical cancer treatment." (PMID 36403055, 2022). "CCL2 is greatly expressed in the tumor microenvironment of cervical cancer." (PMID 36403055, 2022). "CCL2 expression is a marker of cervical cancer, and enhanced expression of CCR2 may correlate with poor overall survival." (PMID 34464477, 2021). "A previous study indicated that CCL2 could promote the invasion of pancreatic ductal adenocarcinoma and the metastasis in cervical cancer." (PMID 34335109, 2021). "Our study demonstrated that SC-derived CCL2 modulated the PNI of cervical cancer." (PMID 32064233, 2020). "We did, however, observe a high level of uptake in the cervical cancer-derived (HeLa-CCL2) cells." (PMID 32402089, 2020). "Meanwhile, we detected high expression of CCL2 in SCs, while cervical cancer cells expressed lowly." (PMID 32064233, 2020). "In this study, we explored the role of CCL2, identified its association with SCs and elucidated its potential clinical value in predicating PNI and selecting the appropriate surgical method for cervical cancer." (PMID 32064233, 2020).
cervical carcinoma (continued). "Initial experiments evaluating the siRNA efficacy were performed using the human cervix carcinoma cell line, HeLa-CCL2, which supports both HeV replication and RNAi mediated gene silencing, thus providing a model cell to assess RNAi mediated HeV reductions in human cells." (PMID 23691205, 2013). "CCL2 expression in RSC96 cells was markedly induced by its co-culture with cervical cancer cells, and its expression could be induced by the administration of recombinant NMB, while this induction was abolished by the inhibition using PD168368 or deficiency of NMB." (PMID 39214988, 2024). "Furthermore, CCL2 induced the epithelial-mesenchymal transition of cervical cancer cells, thereby promoting their metastasis and facilitating the perineural invasion of cervical cancer." (PMID 36403055, 2022). "Moreover, the CCL2/CCR2 axis mediated PNI of cervical cancer in vitro and in vivo." (PMID 32064233, 2020). "Studies employing coculture models of SCs with cervical cancer cell lines, such as HeLa and ME180, have demonstrated that SCs secrete the chemokine CCL2, impacting the immune landscape in the TME." (PMID 41583906, 2026). "Moreover, combined examination of NMB and CCL2 showed the discrimination of PNI with the AUC value of 0.914 (95% CI 0.828-1.000) in cervical cancer as compared to that of NMB or CCL2 alone, which may be clinical effective for the preoperative evaluation of PNI." (PMID 39214988, 2024). "We previously reported that Schwann cell-derived CCL2 can promote the migration of tumor cells along the regenerated neurites, thereby forming PNI in cervical cancer." (PMID 39214988, 2024). "Furthermore, using both serum CCL2 and NMB, it presented a better discrimination in predicting PNI with an AUC of 0.919 (95% CI 0.838-1.000), suggesting that the combined examination of NMB and CCL2 may be a useful approach to diagnose PNI in cervical cancer patients." (PMID 39214988, 2024). "Both CCL2 and its receptor CCR2 have already been described several times in various malignant diseases and there are also corresponding citations for cervical cancer." (PMID 34833360, 2021). "SC-derived CCL2 bound to its receptor CCR2 and promoted the proliferation, migration, invasion, and epithelial-mesenchymal transition (EMT) of cervical cancer cells." (PMID 32064233, 2020). "We identified the CCL2/CCR2 axis as a potential marker to predict the PNI and affect the nerve preservation for cervical cancer." (PMID 32064233, 2020). "In previous studies, T. vaginalis infection induced the production of inflammatory cytokines such as IL-1β, IL-6, CCL2 and CXCL8 in prostate epithelial cells as well as cervical cancer cells." (PMID 32196489, 2020). "Monocyte Chemoattractant Protein-1 (MCP-1/CCL2) is a well-known TAM chemoattractant widely expressed in tumors, including breast, bladder, ovarian and cervical cancers." (PMID 28475599, 2017). "SF regulated the expression of chemokines CCL2, CCL5, CXCL1, CXCL2, CXCL3, CXCL8 (IL-8), and CXCL11 all of which play vital role in cervical cancer inflammation and tumorigenesis." (PMID 27446968, 2016). "It is likely that SF-induced CCL2 and CCL5 can act in similar manner to enhance cervical cancer cell migration, invasion, and metastasis." (PMID 27446968, 2016). "In this study, we also found that NMB induced the secretion of CCL2 by Schwann cells via a NMBR-dependent induction of a Ca2+ influx, which determines this NMB-NMBR-CCL2 axis in the activation of Schwann cells and the initiation of PNI in cervical cancer." (PMID 39214988, 2024). "Cervical carcinoma cells have been shown to present a lower CCL2 secretion in response to CD40 ligation compared to non-tumorigenic HPV-positive cells." (PMID 37970926, 2023). "Western blot and ELISA results revealed elevated secretion of CCL2 from CAFs rather than cervical cancer cells after IR with 8 Gy." (PMID 36900416, 2023).
cervical carcinoma (continued). "Furthermore, SC-produced CCL2 was shown to promote the proliferation, migration, invasion, and EMT of cervical cancer cells." (PMID 36551618, 2022). "Another in vitro study showed that overexpression of CCL2 in cervical cancer ME180 cells using viral vectors did not affect their proliferation." (PMID 34833360, 2021). "In cervical cancer, one research found that ENG significantly reduced the secretion of CCL2 via blocking NF-κB signaling pathway, which could be considered as an inhibitor of NF-κB." (PMID 34717710, 2021). "Previous studies have reported that the CCL2 mRNA expression in cervical carcinoma cells were related to local recurrence and distant metastasis significantly and the absence of CCL2 expression indicated an increased survival." (PMID 32064233, 2020). "Thus, the role of CCL2 and its receptor in PNI of cervical cancer is an emerging field of research." (PMID 32064233, 2020).